SLC2A1 (solute carrier family 2 member 1)
Diseases named in the same sentence as SLC2A1 in open-access papers (continued):
Sharing a sentence is not in itself a finding about the gene and the disease.
lung adenocarcinoma (68 papers, 2013 to 2026). A carcinoma that arises from the lung and is characterized by the presence of malignant glandular epithelial cells. "In LUAD, increased SLC2A1 expression after surgical resection of lung adenocarcinoma is associated with poor prognosis." (PMID 40092704, 2025). "Meanwhile, we found that the expression level of SLC2A1 was significantly associated with the prognosis of lung adenocarcinoma patients, and patients in the high-expression SLC2A1 group had a significantly lower overall survival rate (HR = 1.87, P<0.001)." (PMID 38390340, 2024). "The oncogenic long ncRNA plasmacytoma variant translocation 1 was shown to sponge miR-378c in lung adenocarcinoma and prevent miR-378c binding to SLC2A1, resulting in an increase in SLC2A1 levels." (PMID 35755805, 2022). "Groups based on SLC2A1 expression were used in this study to identify associated ceRNA networks and potential prognostic markers in lung adenocarcinoma." (PMID 34906142, 2021). "SLC2A1 expression and glucose metabolism were increased in tumor-associated neutrophils from mouse models of lung adenocarcinoma compared with normal neutrophils, and tumor growth was slowed and radiotherapy effects were enhanced when SLC2A1 expression was absent in tumor-associated neutrophils." (PMID 39165641, 2024). "In bulk lung adenocarcinoma cohorts, high SLC2A1 expression stratified patients with poorer survival." (PMID 41571939, 2026). "Previous research has identified SLC2A1 as a potential prognostic biomarker for immunotherapy in lung adenocarcinoma." (PMID 40746529, 2025). "The function of SLC2A1 in lung adenocarcinoma (LUAD) was rigorously examined using an integrated approach, encompassing bioinformatics analysis, as well as in vivo and in vitro experiments." (PMID 40824962, 2025). "Tumor tissues from 18 patients with lung adenocarcinoma were collected subsequently, and the correlation between SLC2A1 expression level and microvessel density was observed by immunohistochemical staining." (PMID 38390340, 2024). "Meanwhile, we further verified the role that SLC2A1 mediates VEGFA secretion in lung adenocarcinoma tissues." (PMID 38390340, 2024). "The study revealed that RRM2, SLC2A1, DDIT4, and VDAC2 were positively associated with the survival risk of lung adenocarcinoma patients." (PMID 39311766, 2024). "HIF1A and SLC2A1 expression was significantly higher in lung adenocarcinoma tissues than in adjacent normal tissues." (PMID 39858431, 2024). "We performed an expression analysis of HIF1A, and SLC2A1 in lung adenocarcinoma using the CPTAC dataset." (PMID 39858431, 2024). "MRNA expression levels of TIMP1, S100P, HMMR, F2RL1, KRT6A, and SLC2A1 were significantly increased in lung adenocarcinoma cell lines compared to16HBE, which were consistent with our bioinformatics analysis results." (PMID 35830566, 2022). "Employing 117 machine learning algorithm combinations, we develop a robust five-gene prognostic signature (FAM83A, RHOV, CPS1, STRIP2, SLC2A1) for lung adenocarcinoma (LUAD) with area under the curve values of 0.692, 0.688, and 0.614 for 1-, 3-, and 5-year overall survival, respectively." (PMID 42062606, 2026). "We examined the expression levels of SLC2A1 and VEGFA in the tumor tissues of 18 lung adenocarcinoma patients by immunohistochemical staining, and the IHC results showed that high expression of SLC2A1 was significantly correlated with the increased secretion of VEGFA." (PMID 38390340, 2024). "Additionally, from an analysis of a public database, we showed that SLC2A1 expression was significantly higher in lung adenocarcinoma compared with adjacent normal tissues." (PMID 39858431, 2024). "HIF1A expression was correlated with CEBPB and SLC2A1 in lung adenocarcinoma." (PMID 39858431, 2024).
lung adenocarcinoma (continued). "Our study identified a novel m6A-related ferroptosis-associated six-gene signature (comprising SLC2A1, HERPUD1, EIF2S1, ACSL3, NCOA4, and CISD1) for predicting lung adenocarcinoma prognosis, yielding a useful prognostic biomarker and potential therapeutic target." (PMID 37072786, 2023). "Down-regulation of SLC2A1 can suppress the progression of lung adenocarcinoma." (PMID 35368652, 2022). "The progression of lung adenocarcinoma can be inhibited by inhibiting SLC2A1 expression." (PMID 34630529, 2021). "In our study, we found the characteristic genes that affected lung adenocarcinoma through the propionate pathway included LDHA, KYNU, SLC2A1, CFTR, and MAOB." (PMID 41003841, 2025). "To further evaluate the impact of hypoxia-related genes on lung adenocarcinoma cells, we conducted RT-PCR and in vitro experiments, focusing on the expression of SLC2A1 and XPNPEP1 genes which promote the proliferation of lung adenocarcinoma cells." (PMID 37576511, 2023). "High SLC2A1 expression correlates with poor prognosis in patients with surgically resected lung adenocarcinoma (LUAD), which suggests that SLC2A1 is a promising biomarker for LUAD." (PMID 34079759, 2021). "Based on GEPIA database, seven of the top ten co-expressed genes were highly expressed in lung adenocarcinoma (DSC2, SLC2A1, ARNTL2, ERO1L, ECT2, ANLN and LAMC2)." (PMID 32095325, 2020). "The amplified products were subjected to agarose gel electrophoresis, and six samples all gave clear bands in the correct region indicated by the marker, confirming that the six predicted six-HRGs (STC1, PFKL, HK1, PDK3, SLC2A1, XPNPEP1) were all expressed in lung adenocarcinoma A549 cells." (PMID 37576511, 2023). "Knock-down of SLC2A1 or XPNPEP1 substantially suppressed the proliferation and migration of A549 cells, demonstrating that the expression of these genes promotes the proliferation of lung adenocarcinoma tumors." (PMID 37576511, 2023).
ovarian carcinoma (67 papers, 2003 to 2026). A malignant neoplasm originating from the surface ovarian epithelium. "SLC2A1 is the most extensively studied in a wide range of malignancies, like such as prostate, ovarian cancer, and breast as well as bladder cancers, while abnormally high GLUT1 expression correspondence with the malignant phenotype of tumors." (PMID 37443106, 2023). "We observed that MAP1LC3B was inversely correlated with IL6R and SLC2A1 mRNA expression in ovarian cancer patients TCGA data set." (PMID 36675246, 2023). "SLC2A1 mediates glycolysis, affects the tumor microenvironment, and affects the metabolism and metastasis of ovarian cancer cells." (PMID 36110943, 2022). "The highest alteration frequency of SLC2A1 appeared in the ovarian carcinoma patients with “amplification” as the primary type." (PMID 36358765, 2022). "Short-term glucose starvation in ovarian cancer cells was shown to upregulate SLC2A1 and G6PD mRNA and protein levels." (PMID 28412735, 2017). "Of note, elevated expression of SLC2A1 and G6PD, as well as increased PPP and OXPHOS activity, have recently been linked with resistance of putative ovarian cancer stem cells to glucose deprivation." (PMID 28412735, 2017). "In line with a published study on ovarian cancer stem cells that are more resistant to glucose deprivation, glucose-restricted OVCAR3 cells induced G6PD and SLC2A1 expression at the transcriptional level." (PMID 28412735, 2017).
colon cancer (64 papers, 2002 to 2025). "Our results suggest that methylation of SLC2A1 is associated with immunosuppression in colon cancer." (PMID 36065306, 2022). "Our study substantiates that the ferroptosis and autophagy-co-associated gene SLC2A1 is involved in tumor immune regulation and tumor prognosis in colon cancer." (PMID 36065306, 2022). "Hypermethylation of SLC2A1 is associated with T cell exhaustion and suppression of the immune microenvironment in colon cancer, a process which is most likely mediated by ferroptosis and autophagy." (PMID 36065306, 2022). "The expression level of SLC2A1 itself is associated with the prognosis of colon cancer patients." (PMID 36065306, 2022). "We utilized four machine learning algorithms to identify three key ferroptosis-related genes (TXNIP, SLC2A1, ATF3) that are closely associated with the development and prognosis of colon cancer from 52 differentially expressed genes." (PMID 38244591, 2024). "On the other hand, SLC2A1 promotes immune evasion and liver metastasis in colon cancer by inducing regulatory T cells." (PMID 38831301, 2024). "Despite these limitations, our model successfully identified prognostic markers for colon cancer, particularly genes such as SLC2A1 and ADCY5, which are also supported by existing literature." (PMID 39678375, 2024). "In conclusion, our study demonstrates that SLC2A1 is involved in the regulation of ferroptosis and autophagy in colon cancer, which in turn regulates tumor immunity and affects tumor progression." (PMID 36065306, 2022). "Our results suggest that SLC2A1 further modulates the immune microenvironment by regulating ferroptosis and autophagy processes in colon cancer, thereby affecting disease prognosis." (PMID 36065306, 2022). "Glycolysis and fermentation of major metabolic genes were highly expressed inside EndMT, and SLC2A1 was highest expressed gene in colon cancer." (PMID 35755820, 2022). "The SLC2A1 gene was related to the metabolic shift of colon cancer, and the HCN4 gene was correlated with low survival rate of multiple cancers." (PMID 31207989, 2019). "Therefore, we determined that the SLC2A1 gene not only plays an important role in ferroptosis but also plays an indispensable role in autophagy in colon cancer." (PMID 36065306, 2022). "Our results also indicate that SLC2A1 may become an effective therapeutic target for colon cancer in the future." (PMID 36065306, 2022). "In order to explore the clinical relevance of SLC2A1 expression in colon cancer, clinical data from TCGA were downloaded for analysis and SLC2A1 was found to have high predictive power for the variable SLC2A1 in predicting the outcomes of Normal and Tumor (AUC = 0.968, CI = 0.957–0.979)." (PMID 36065306, 2022). "We have examined whether miR-328 directly regulates SLC2A1/GLUT1 expression in colon cancer cells." (PMID 29374351, 2018). "SLC1A4, SLC2A1, SLC3A2, SLC6A8, and SLC7A5 are transported as mRNAs by lung- and colon cancer-related exosomes." (PMID 41440381, 2025). "Collectively, our results were consistent across several datasets, suggesting that ADCY5 and SLC2A1 could potentially serve as robust prognostic biomarkers for CC, and underscore a significant role played by the microenvironment in the progression of colon cancer." (PMID 39678375, 2024). "Thus, our model identifies important markers such as SLC2A1 and ADCY5 which can provide valuable prognostic information for colon cancer patients, potentially guiding treatment decisions." (PMID 39678375, 2024). "Furthermore, miR‐328 expression is reduced in colon cancer patients and thus inversely correlates with the classically reported upregulated SLC2A1/GLUT1 expression in tumors." (PMID 29374351, 2018). "It has to be noted though that the protein product of SLC2A1, GLUT1, is not detectable in healthy human colon tissue, but only in colon cancer serving as a marker for poor prognosis." (PMID 15882471, 2005).
prostate carcinoma (63 papers, 2010 to 2025). A carcinoma that arises from epithelial cells of the prostate gland. "MiR-378a-3p was found to be downregulated in prostate cancer, and miR-378a-3p was revealed to reduce SLC2A1 expression to interfere with glycolytic pathway and cell proliferation." (PMID 35755805, 2022). "In prostate cancer, miR-378a and miR-132 can modulate SLC2A1 expression." (PMID 35755805, 2022). "Solute carrier family 2A (facilitated glucose transporter, member 1) [SLC2A1; also known as glucose transporter 1 (GLUT1)] protein is increased in kidney, oral cavity, breast, and prostate cancers." (PMID 25714027, 2015).
Hypoglycemia (51 papers, 2010 to 2025). A decreased concentration of glucose in the blood. "Hypoglycemia is known to upregulate SLC2A1 and SLC2A3, optimizing glucose uptake when blood glucose levels are low, further supporting the observed response in the RES treatment." (PMID 41012809, 2025). "Historically, homozygous mutation in SLC2A1 that encodes glucose transporter GLUT1, is the cause for autosomal recessive glucose transporter defect disorder in which the hypoglycemia induced seizure is the major clinical feature." (PMID 28074849, 2017). "In sheep, FGR induced by placental embolization results in fetal hypoxia and hypoglycemia and is associated with reductions in SLC2A1 mRNA and placental glucose uptake, but the intra-amniotic infusion of IGF1 into these fetuses increased the placental expression of SLC2A1 mRNA." (PMID 37374044, 2023). "Interestingly, patient 27 with a SLC2A1 mutation causing glucose transporter type 1 (GLUT1) deficiency syndrome, was initially suspected to have a neurometabolic disorder due to the presence of systemic hypoglycaemia, cerebellar ataxia, spasticity and mild intellectual disability." (PMID 33446253, 2021).
Obesity (48 papers, 2009 to 2026). Accumulation of substantial excess body fat. "A panel of hypoxia-regulated genes (VEGF, ADM, LDHA, SLC2A1) showed consistently higher mean values in the endometrium of women with obesity and in uteri of mice with increased weight vs normal controls, although statistical significance was not reached." (PMID 33836495, 2021). "First, we identified gene sets related to the function of each obesity-related serum factor: HG/HI (Insr, Irs1, Rps6kb1, Slc2a4, Slc2a5, Slc2a1), TNF-α (Tnfrsf1a, Tradd, Traf2, Fadd), IL-6 (Il6ra, Il6st, Jak1), and fatty acids (PA, LA, Chol; Ffar1, Ffar4, Ppara, Pdk4, Pgc1a)." (PMID 37047207, 2023).
bladder cancer (46 papers, 2003 to 2025). "Ankfn1, Gstt2, Plec, Gphn, Fmo5, Cmss1, Ahnak, Mecom, Slc2a1, Gsta4, Kras, Peak1, and Hmga2 were associated with worse disease-free survival in bladder cancer patients." (PMID 39769061, 2024). "Gstt2, Gphn, Plec Cmss1, Ahnak, Slc2a1, Gsta4, Kras, Peak1, and Hmga2 were associated with worse overall survival in bladder cancer patients, and the association was significant for Gstt2 and Ahnak." (PMID 39769061, 2024). "SLC2A1 encodes GLUT1, a glucose transporter commonly upregulated in many forms of cancer, including bladder cancer." (PMID 38339062, 2024). "GLUT1 (SLC2A1) is a glucose transporter protein highly associated with bladder cancer malignancy." (PMID 38339062, 2024). "An 11-gene signature (Hmga2, Peak 1, Kras, Slc2a1, Ankfn1, Ahnak, Cmss1, Fmo5, Gphn, Plec, Gstt2) had the most substantial impact on disease-free survival in bladder cancer patients." (PMID 39769061, 2024). "KRT17 expression was significantly high in pT1 (11.5-fold, p = 2.7 x 10-7), pT2 and higher stages (15.0-fold, p = 4.0 x 10-4), G2 (1.4-fold, p = 0.022) and G3 bladder cancer (6.7-fold, p = 1.8 x 10-6), which was consistent with the expression of SLC2A1 and GPRC5A." (PMID 30214686, 2018). "GPRC5A expression was also significantly elevated in pTis (8.3-fold, p = 0.0084), pT1 (19.5-fold, p = 2.1 x 10-8), G2 (2.0-fold, p = 0.048) and G3 bladder cancer (11.5-fold, p = 8.1 x 10-7) therefore may be useful to supplement SLC2A1 especially for the detection of pTis bladder cancer." (PMID 30214686, 2018). "By identifying three uEV biomarkers (mucin-1 (MUC-1), coiled-coil domain containing 25 (CCDC25), and solute carrier family 2 member 1 (GLUT1)), Pt@CP-based immunoassays are able to detect bladder cancer with high clinical specificity and sensitivity." (PMID 40072370, 2025). "Urinary EV SLC2A1, GPRC5A and KRT17 were overexpressed in pT1 and higher stage bladder cancer by 20.6-fold, 18.2-fold and 29.5-fold, respectively." (PMID 30214686, 2018). "Moreover, downregulation of CA9, NDRG1, SLC2A1, VEGFA, and upregulation of MDM2 were further verified in an additional bladder cancer cell line, 5637 cells." (PMID 38339062, 2024). "SLC2A1 was able to detect cytology-negative/suspicious bladder cancer (N=115) with AUC 0.68 and recurrent bladder cancer (N=77) with AUC 0.62." (PMID 30214686, 2018). "SLC2A1 outperformed urine cytology and bladder tumor antigen (BTA) especially for the detection of all the stages (AUC 0.70 vs. 0.57 to 0.63), pTa (AUC 0.64 vs. 0.49 to 0.56) and pT1 bladder cancer (AUC 0.86 vs. 0.60 to 0.82)." (PMID 30214686, 2018). "SLC2A1 was significantly overexpressed in pTa (2.6-fold, p = 0.0020), pT1 (35.6-fold, p = 2.0 x 10-8), pT2 and higher stages (11.4-fold, p = 0.016), G2 (2.9-fold, p = 0.0018) and G3 bladder cancer (15.2-fold, p = 1.1 x 10-8) compared to the non-BC control groups (DC and NRT)." (PMID 30214686, 2018).
non-small cell lung carcinoma (46 papers, 2008 to 2025). A group of at least three distinct histological types of lung cancer, including non-small cell squamous cell carcinoma, adenocarcinoma, and large cell carcinoma. "SLC2A1 is identification to be differentially expressed genes in non-small cell lung cancer." (PMID 35830566, 2022). "SLC2A1 is a gene encoding one such cell membrane glycoprotein, which has been shown to be involved in glucose transport in a range of tumors including oral squamous cell carcinoma, non-small cell lung carcinoma, and non-gastrointestinal stromal tumor soft tissue sarcomas." (PMID 32854182, 2020).
thyroid cancer (44 papers, 2012 to 2025). "The loss of PTEN in thyroid cancer cells resulted in the altered plasma membrane expression of SLC2A1, and increased glucose uptake." (PMID 36078116, 2022). "Although one study reported a close correlation between the expression of SLC2A1/SLC2A3 mRNA and that of GLUT1/GLUT3 proteins in thyroid carcinoma, further studies are needed to investigate whether the expression of SLC2A mRNA correlates with expression of GLUT protein mRNA in CRC." (PMID 30943948, 2019). "For instance, HIF-1α can increase GLUT1 and GLUT3 expression, increase the uptake of glucose by thyroid cancer cells, and provide substrates for glycolysis to meet their energy needs through SLC2A1 (encoding GLUT1) and SLC2A3 (encoding GLUT3)." (PMID 40917751, 2025).
Alzheimer disease (42 papers, 2011 to 2026). A progressive, neurodegenerative disease characterized by loss of function and death of nerve cells in several areas of the brain leading to loss of cognitive function such as memory and language. "In the brain tissue of Alzheimer’s disease (AD) patients, the expression of SLC2A1 is significantly reduced, inversely correlated with Aβ deposition." (PMID 41425581, 2025). "Decreased Fpn expression and abnormal iron deposition significantly increased NOX4, 4-HNE, and MDA levels in damaged astrocytes of cerebral cortex, and five hub genes (JUN, SLC2A1, TFRC, ALB, and NFE2L2) closely related to ferroptosis were identified in Alzheimer's disease (AD) patients." (PMID 36062196, 2022).
cervical cancer (40 papers, 2003 to 2025). A primary or metastatic malignant neoplasm involving the cervix. "High expression of SLC2A1 in high-grade CIN with high-risk human papillomavirus (HR-HPV) infection indicates a high risk of cervical cancer." (PMID 37042849, 2023). "This study also confirms that SLC2A1 and CA2 are highly expressed, and that CUX1 is weakly expressed, in cervical cancer tissues." (PMID 37042849, 2023). "This study predicts that anti-CTLA-4 therapy may serve as an immunotherapeutic agent for managing cervical cancer and that the expression of CUX1, SLC2A1, and CA2 genes validated by clinical samples may serve as important targets for treatment modalities in cervical cancer." (PMID 37042849, 2023).
oral squamous cell carcinoma (39 papers, 2010 to 2025). "The GLUT1 (gene: SLC2A1) and GLUT3 (gene: SLC2A3) proteins are significant indicators of a poor prognosis outcome in oral squamous cell carcinoma, probably because of the enhanced glycolytic metabolism of more aggressive neoplastic cells." (PMID 29228563, 2017).